IL11RA (interleukin 11 receptor subunit alpha)
Diseases named in the same sentence as IL11RA in open-access papers (continued):
Sharing a sentence is not in itself a finding about the gene and the disease.
cancer (22 papers, 2007 to 2026). A tumor composed of atypical neoplastic, often pleomorphic cells that invade other tissues. "Extensive research indicates that IL-11 and its receptor IL11RA are involved in crucial processes such as cell proliferation, differentiation, invasion, and metastasis in various cancers, significantly influencing tumorigenesis and progression." (PMID 40755754, 2025). "The low affinity Fc gamma receptor (FCGR2A/CD32), the cytokine receptor CX3CR1 and IL11RA were also higher in cancers with RD." (PMID 30967156, 2019). "IL-11 transmits signals through its unique receptor, IL-11Rα, which couples with the common receptor subunit GP130 to activate the downstream STAT3 signaling pathway, a pathway that is closely associated with cancer pathogenesis." (PMID 29100303, 2017). "Positive immunostaining for IL11 was detected in all cancer tissues examined; meanwhile IL11Rα staining was present in all cancer tissues except two from grade 3." (PMID 20553623, 2010). "Given that IL-11Rα has been proposed as a target in human cancer, our results provide clues for the rational design of targeted drugs." (PMID 18941632, 2008). "Interleukin-11 is accompanied by its transmembrane receptor IL-11 receptor-alpha (IL-11Rα) and stimulates the proliferation of the breast neoplastic cells with the simultaneous growth of the primary cancer cells and the migration of the cancer cells into distant organs." (PMID 30648081, 2018). "A functional IL-11Rα subunit might trigger signal transduction by IL-11 in human cancer cells cultured under hypoxic conditions." (PMID 30197757, 2018). "The effect could be abrogated by suppressing STAT3 phosphorylation or silencing IL-11Rα expression in cancer cells." (PMID 27922075, 2016). "IL-11 and its receptor, interleukin-11 receptor α (IL-11Rα) activate STAT3 signaling, which correlates with poor patient prognosis in most human cancers." (PMID 37240247, 2023). "Other genes overexpressed in Cluster 1 were chemokine and cytokine related genes (CCL15, CCL18, TNF, IL11RA, XCR1), the immune checkpoint protein PD-1 (PDCD1), and cancer-related genes (SSX1 and MAGEA4)." (PMID 33298930, 2020). "Both IL11 and IL11Rα localized to vascular endothelial and smooth muscle cells while IL11 also localized to subsets of leucocytes in the cancer tissues." (PMID 20553623, 2010). "FNBP1, FRMD3, IGSF10, IL11RA, and TOX2 have known roles in cancer." (PMID 38398114, 2024).
infection (3 papers, 2007 to 2021). The state of being infected such as from the introduction of a foreign agent such as serum, vaccine, antigenic substance or organism. "The use of the selected LncRNA and IL11RA mRNA in assessing the severity of infection was made efficient using ROC curve analysis, with the ideal cutoff values of 15.95 for IL11RA mRNA (AUC = 0.803) and 40.5 for LncRNA RP11-773H22.4 (AUC = 0.777)." (PMID 34831321, 2021). "This is consistent with our whole lung findings, where IL-11Rα remained unchanged during infection." (PMID 31415618, 2019).
IL11RA also shares sentences with these, for which no sentence is quoted: acute myocardial infarction (2 papers); idiopathic pulmonary fibrosis (2); ovarian carcinoma (2); autoimmune thyroid disease (1); breast tumours (1); cardiovascular disorder (1); Crouzon syndrome (1); diabetes (1); endometriosis (1); endothelial dysfunction (1); female infertility (1); Hypertension (1); leiomyoma (1); lymphoma (1); metastatic prostate carcinoma (1); multiple sclerosis (1); primary immunodeficiency (1); scoliosis (1); Stroke (1); synovitis (1); systemic lupus erythematosus (1); viral infection (1).